LEP (leptin)
Diseases named in the same sentence as LEP in open-access papers (continued):
Sharing a sentence is not in itself a finding about the gene and the disease.
Insulin resistance (continued). "Chronic hyperleptinemia in HFrEF might be a result of chronic inflammation, resulting insulin resistance, ectopic leptin production from cardiomyocytes or vascular cells, and hypoxia-induced leptin production via various tissues due to hypoperfusion." (PMID 39682585, 2024). "Serum leptin levels are significantly correlated with body mass index (BMI) and insulin resistance." (PMID 38737668, 2024). "LEP, a cytokine exacerbating insulin resistance with pro-inflammatory properties, could contribute to accelerated aging." (PMID 38615017, 2024). "Influencing mechanisms may involve insulin, IGF-1, insulin resistance, endogenous hormones, leptin, adiponectin, inflammatory factors and other factors." (PMID 39011481, 2024). "Accelerated appetite during the detraining period could result from changes in leptin and insulin resistance in OLETF rats." (PMID 38872474, 2024). "Moreover, improvements in insulin resistance markers, leptin levels, and cord blood C-peptide levels were observed in women in the intervention group." (PMID 38592297, 2024). "However, antioxidants and exercise in the mother have been shown to improve the offspring’s metabolism, with improvements in leptin, triglycerides, adiponectin, and insulin resistance, as well as in the fetal birth weight through epigenetic mechanisms." (PMID 38785533, 2024). "Insulin resistance is linked to the buildup of visceral adipose tissue, which potentiates proinflammatory cytokines and adipokines, including IL-6, TNF-α, and leptin, enhancing lipolysis and stimulating the ovaries to produce androgens, leading to hyperandrogenemia." (PMID 39064282, 2024). "Metabolically, evidence suggests a role for maternal leptin and insulin resistance." (PMID 38898228, 2024). "It has been demonstrated that patients with AN have significantly decreased plasma leptin and markedly increased plasma adiponectin levels, and the increased adiponectin levels may serve as a compensatory mechanism for insulin resistance in patients with AN." (PMID 38921471, 2024). "Adiponectin, leptin, and visfatin levels, along with Homeostasis Model Assessment-Insulin Resistance (HOMA-IR) index, were higher whereas brachial artery flow-mediated vasodilatation was lower in LN cases than in SLE without renal involvement in a recent study." (PMID 39201667, 2024). "The excessive production of PGH, hPL and leptin serves to exacerbate maternal insulin resistance." (PMID 39683486, 2024). "A reduction in leptin levels may indicate improved leptin sensitivity, which could reduce inflammation and insulin resistance, thereby restoring metabolic balance and supporting beneficial outcomes in insulin sensitivity and lipid metabolism." (PMID 39770882, 2024). "Furthermore, this ratio presents a stronger correlation with insulin resistance than leptin or adiponectin alone, which is useful in the identification of those individuals at risk of MetS." (PMID 37049561, 2023). "Leptin can lead to uncontrolled eating and weight gain promoting insulin resistance." (PMID 36675592, 2023). "A weaker negative association between FM and EI at higher body fatness is in line with the notion of leptin and insulin resistance, which may alter central and peripheral sensitivity to appetite-related feedback signals." (PMID 37482777, 2023). "Accordingly, we used CRP knockout (KO) rats to construct a PCOS model to explore whether CRP gene deletion affects insulin resistance, hepatic glucose homeostasis and leptin bioactivity in PCOS rats." (PMID 37660067, 2023). "A second possible explanation is that high BMI may affect tumor proliferation and prognosis through hyperinsulinemia, insulin resistance, insulin-like growth factor, leptin, and other pathways." (PMID 37941781, 2023). "Leptin is mainly produced by adipose tissues, leading to insulin resistance development." (PMID 37711887, 2023).
Insulin resistance (continued). "According to studies conducted on diabetic patients, curcuminoids enhance insulin resistance, decrease levels of leptin, resistin, interleukin (IL)-6 IL-1β, and tumor necrosis factor-α, increase the release of adiponectin, and decrease glucose and insulin levels." (PMID 37240220, 2023). "The relative therapeutic failure of leptin replacement in the A-ZIP/F1 mouse suggested that leptin deficiency was not the sole cause of insulin resistance in this murine model of CGL." (PMID 38260129, 2023). "These correlations may indicate that the increment in salivary leptin observed in our study could be due to the situation of insulin resistance and inflammation occurring in DM, since leptin can act as proinflammatory cytokine." (PMID 37223639, 2023). "In addition, weight loss caused a greater decrease in intrahepatic triglyceride content and greater changes in the plasma leptin/adiponectin ratio, plasma metabolites, and PAI-1 concentrations that are associated with insulin resistance." (PMID 37159276, 2023). "In addition, the strong associations of ME1 with leptin, PPAR-γ, and TNF-α support significant role(s) for hepatic ME1 in predisposition for insulin resistance and type II diabetes mellitus." (PMID 37047583, 2023). "Dysregulation of Cdc42, whether induced by external or internal factors, appears to be an important contributor to the development of leptin and insulin resistance." (PMID 38068822, 2023). "Thus, higher LAR values have been considered a better marker of insulin resistance and metabolic syndrome than serum leptin or adiponectin levels." (PMID 36967781, 2023). "Thus, rats supplemented with leptin during lactation maintained leptin levels and preserved features of insulin resistance, i.e., the HOMA index." (PMID 38203399, 2023). "Vice versa, leptin can influence insulin and insulin resistance." (PMID 38068822, 2023). "Increased plasma leptin levels have often been associated with insulin resistance in human subjects, and a negative correlation between fasting plasma leptin and insulin sensitivity has been reported after adjusting for BMI." (PMID 37964253, 2023). "Leptin levels are positively associated with BMI, HOMA-IR, and serum triglycerides and negatively with serum HDL in mostly normal weight health individuals suggesting that leptin increases with BMI as well as in those with insulin resistance." (PMID 36200436, 2023). "Finally, in two studies from Latin America (Mexico and Colombia), serum leptin, insulin, adiponectin levels, and a homeostatic model assessment for insulin resistance (HOMA-IR) predicted the variation in excessive GWG or were associated with higher pBMI." (PMID 36986260, 2023). "Leptin is an important adipokine whose significant relations with body composition and the level of insulin resistance in the population of males with MetS indicate that application of physical training in order to improve health conditions features a therapeutic potential." (PMID 37109160, 2023). "In addition, in high-fat diet-induced diabetes models of C57BL/6J mice and albino rats, interventions with curcumin reduced circulating glucose and leptin, with a concomitant increase in adiponectin and overall improvement of insulin resistance." (PMID 37047589, 2023). "Obesity is associated with an increase in the secretion of adipocytokines, such as TNF-α, leptin, resistin, IL-1β or IL-6, by immune cells as well as adipocytes, which leads to the progress of insulin resistance through a number of processes, including the activation of Ser/Thr kinases." (PMID 36826001, 2023). "The adiponectin, leptin and resistin alternations translate to the worsening of maternal insulin resistance as well as metabolic stress and, in consequence, the promotion of an inflammatory environment, altered placenta functions, and finally, unfavorable conditions for the developing fetus." (PMID 37764842, 2023).
Insulin resistance (continued). "Likewise, the effects of the compounds on glucose tolerance, insulin resistance, as well as insulin and leptin levels, have been evaluated." (PMID 36901928, 2023). "Leptin is decreased in lipoatrophy, and leptin supplementation improves insulin resistance." (PMID 37793000, 2023). "The effect of fluctuations in visceral fat on leptin and lipocalin may also furthermore have some effects on the development of insulin resistance and T2D, but further studies are still needed to explain this association." (PMID 37474925, 2023). "GDM is mainly characterized by insulin-resistance and leptin-resistance." (PMID 37497352, 2023). "Thus, HFD consumption in low-5HT animals resulted in hyperglycemia and hyperinsulinemia, glucose intolerance and insulin resistance, as well as elevated blood leptin, cholesterol and triglycerides (TG) levels, and decreased glucagon levels." (PMID 36768493, 2023). "Hesperidin could also affect insulin levels and insulin resistance by modulating inflammation since it has been shown that inflammatory markers, including leptin, IL-6, and TNF-α, play a role in the pathogenesis of DM and the development of insulin resistance." (PMID 37502716, 2023). "In addition, through pro-inflammatory effects, elevated serum leptin levels correlate with insulin resistance, arterial stiffness, elevated blood pressure." (PMID 36839226, 2023). "The elevation of LPS depends on TLR to further activate the NF-κB pathway, promoting the release of inflammatory factors, leptin adipose resistin expression, and macrophage M1 proinflammatory phenotype changes, further leading to abnormal insulin resistance and glucose metabolism." (PMID 37072819, 2023). "As expected, sleeve gastrectomy significantly (all p < 0.05) reduced body weight, total white adiposity and the adipokine leptin, as well as markers of insulin resistance (insulin and HOMA), independently of the diet provided after surgical intervention to the experimental animals." (PMID 36834823, 2023). "There is a connection between the hormone leptin, insulin resistance, and abdominal obesity." (PMID 37175603, 2023). "All these results suggested that the females treated with liraglutide have a high tendency to develop adipocyte insulin resistance—an inability to store lipids (or blocked lipolysis) and excrete leptin at sufficient levels to counteract central insulin resistance." (PMID 37929025, 2023). "It is important to consider the impact a reduction in serum leptin may have on insulin resistance in GDM and, therefore, a potential reduction in the short-term and long-term consequences of insulin resistance." (PMID 36650305, 2023). "Also reported was a reduction in circulating lipids, leptin, insulin resistance, and waist circumference." (PMID 37546289, 2023). "L. plantarum and inulin can exert antidiabetic and antioxidant properties via improving insulin resistance and hyperlipidemia as well as hypothalamic levels of insulin, leptin, and oxidative markers in T2DM rats, and their combined recovery effect is superior to that of their use alone." (PMID 37734909, 2023). "Given that variations in the leptin hormone itself are associated with variations in blood glucose levels, it was not surprising to observe that SNPs in the LEP gene were associated with differences in glucose levels and/or insulin resistance." (PMID 37241229, 2023). "Under normal physiological conditions, bloodstream levels of leptin are proportional to fat mass for a given individual suggesting that the increase in leptin is driven by fat mass and that both leptin and insulin resistance are consequences of an increase in fat mass." (PMID 36200436, 2023). "A leptin resistance pathway has been hypothesized, similar to the insulin resistance pathway, whereby the excessive level of leptin has an inhibitory effect on the kisspeptin neurons, the function of the testes, and spermatogenesis." (PMID 38203349, 2023).
Insulin resistance (continued). "Under the long-term stimulation of high concentrations of leptin, the receptor responsiveness of the islets β cells of the body decreased, thereby reducing the inhibitory effect of leptin on insulin synthesis and increasing insulin secretion, leading to hyperinsulinemia and insulin resistance." (PMID 37560059, 2023). "This inflammatory state increases the secretion of proinflammatory cytokines (adipokines), such as tumour necrosis factor alpha (TNFα), interleukins 1 and 6 (IL-1 and IL-6) and leptin, which generates insulin resistance, the inhibition of protein synthesis and an increase in muscle catabolism." (PMID 36626317, 2023). "Leptin can promote insulin resistance and downregulate insulin signaling in various cell models." (PMID 37780623, 2023). "Leptin is accountable for bolstering insulin resistance through various means." (PMID 37762060, 2023). "Therefore, the results of previous studies in which higher levels of leptin are related to higher levels of insulin and, consequently, insulin resistance due to a break in the insulin signaling pathway caused by hyperinsulinemia are supported." (PMID 37299591, 2023). "Increased levels of leptin and decreased levels of adiponectin may promote the development of insulin resistance and type-2 diabetes, hypertension, atherosclerosis, other cardiovascular diseases, and some types of cancer." (PMID 37600013, 2023). "Furthermore, leptin was shown to be associated with elevated CRP levels and insulin resistance, which are both linked to CKD." (PMID 37371050, 2023). "This improvement in insulin resistance may be linked to SSFR-associated changes in the secretion of certain adipokines, such as leptin and IL-6." (PMID 37021835, 2023). "Insulin resistance, abnormal metabolism of fat factors [pro-inflammatory adipokines (leptin, resistin, TNF-α), anti-inflammatory adipokine (adiponectin), specific adipokine Sfrp5], and vitamin D deficiency are all possible causes of abnormal blood lipids in visceral obese individuals." (PMID 37674809, 2023). "Leptin and resistin are responsible for enhancing insulin resistance through various means." (PMID 36826001, 2023). "However, another study concluded that leptin was significantly correlated with BMI, waist circumference, hip circumference, insulin resistance, and lipid parameters." (PMID 37703108, 2023). "Finally, insulin resistance and alterations in adipokine levels, particularly leptin and adiponectin, have been found to play a role in the relationship between lipid and bone metabolism." (PMID 38125793, 2023). "In this sense, leptin and adiponectin or the leptin/adiponectin ratio may be considered surrogate markers of insulin resistance and MS." (PMID 36831072, 2023). "In this context, high plasma leptin levels are positively correlated with insulin resistance." (PMID 35807489, 2022). "In addition, a systematic review of in vitro and in vivo studies reported that ginsenosides regulate glycolipid metabolism, and increase leptin sensitivity and insulin resistance." (PMID 36559300, 2022). "Furthermore, obese patients with insulin resistance have a higher concentration of circulating leptin than normal-weight people." (PMID 36532520, 2022). "ER stress induced central leptin and insulin resistance and increased food intake and weight gain." (PMID 36188456, 2022). "Notably, the adipose tissue plays a key role in inflammation-induced insulin resistance as a massive source of inflammatory cytokines and specific adipokines, including leptin, resistin and adiponectin." (PMID 35327570, 2022). "Insulin resistance is facilitated by leptin, a negative regulator of insulin." (PMID 36532520, 2022). "Altogether, it is concluded that the altered secretions of four adipokines, adiponectin, leptin, visfatin and chemerin, may contribute to the defective production/action of insulin and, concomitantly, insulin resistance." (PMID 35629157, 2022).
Insulin resistance (continued). "Therefore, this study investigated the effect of LEP G2548A on leptin levels and insulin resistance in T2DM among Malaysian subjects." (PMID 36381191, 2022). "Finally, the mediating effect of Fetuin B in insulin resistance induced by leptin was confirmed according to mediation analysis in this obese population." (PMID 35896788, 2022). "However, under certain conditions such as those seen in women with polycystic ovary syndrome, it is likely that leptin and insulin resistance contributes to the neuroendocrine and metabolic phenotype in these subjects." (PMID 36394061, 2022). "Our results indicated a strong relationship between leptin levels and insulin resistance." (PMID 36143007, 2022). "The influence of leptin on insulin resistance is also not yet fully understood." (PMID 35386146, 2022). "Finally, a positive linear correlation was found among ghrelin and leptin relative to resistin levels in the WT animals, which is related to insulin resistance." (PMID 34935299, 2022). "Moreover, SPIONs treatment significantly ameliorates hyperglycemia, insulin resistance, dyslipidemia, leptin, adiponectin, and NEFA." (PMID 36297569, 2022). "The probable mechanism by which both ACE and electro-acupuncture have positive effects in reducing weight in obese patients may be related to its effects in downregulating serum leptin and insulin levels and correcting leptin resistance and insulin resistance." (PMID 35265146, 2022). "LEP is involved in peripheral insulin resistance, impairs the action of insulin on insulin-responsive cells and may induce insulin resistance by affecting insulin secretion." (PMID 36005598, 2022). "In addition, suppression of HSCDA production was accompanied by elevated circulating leptin levels, decreased physical activity and insulin resistance." (PMID 35721743, 2022). "However, we find that MEF‐secreted leptin is insufficient to fully rescue insulin resistance in FF mice, measured by the AUC of the fasting insulin tolerance test." (PMID 35844058, 2022). "Studies have shown that the abundance of Subdoligranulum is positively correlated with microbial richness and HDL-cholesterol levels, and negatively correlated with fat mass, adipocyte diameter, insulin resistance, leptin, insulin, CRP, and IL6 levels in people and animals." (PMID 36611702, 2022). "The high level of leptin leads to glucose intolerance and insulin resistance." (PMID 35743665, 2022). "Regarding the increased levels of leptin in patients with MetS there are several reports confirming their increase, which is mainly related to the mass of adipose tissue, while on the other hand its levels are also related to insulin resistance." (PMID 35712481, 2022). "In the whole course of illness, the abnormal lifestyle or long-term medication history of patients might lead to metabolic disorders, and the occurrence of this condition was closely related to the high levels of leptin, insulin resistance and hs-CRP." (PMID 36090349, 2022). "As there are no previous studies done on the leptin/leptin gene receptor polymorphism in insulin resistance, this study elucidated the role of polymorphism of leptin gene in pregnant insulin resistant women." (PMID 36128550, 2022). "It has been suggested that AN shares genetic variation with various metabolic phenotypes, including fasting insulin, leptin, insulin resistance, type 2 diabetes, and HDL cholesterol, which may be independent of BMI." (PMID 35013117, 2022). "One clinical study indicates that chronic exposure to endogenous GCs leads to insulin resistance, and GCs-induced hyperinsulinemia may act as a mediator of the steroid-induced elevation in leptin levels." (PMID 36699046, 2022). "Besides insulin resistance, accumulated visceral adipose tissue acts as an endocrine organ secreting adipokines, such as leptin and adiponectin, which play an important role in neurodegeneration." (PMID 35803940, 2022).